PSG9 (pregnancy specific beta-1-glycoprotein 9)
Description:
Binds to the small latent transforming growth factor-beta complex, consisting of the N-terminal TGFB1 latency-associated peptide (LAP) and the mature form of TGFB1, thereby leading to the activation of TGFB1. The activation of TGFB1 leads to stimulation of naive CD4(+) T-cells to increase FoxP3 expression and to an increase in the number of FoxP3(+) regulatory T-cells. Induces the differentiation of a suppressive CD4(+)LAP(+)FoxP3(-) T-cell subset. Induces the secretion of TGFB1 in macrophages, but not in activated CD4(+) T-cells. May reduce the expression of several pro-inflammatory cytokines and chemokines by CD4(+) T-cells, including IL2 and IL6.
Synonyms: PS-beta-G-9; PSBG-9; PS-beta-B; PSG11; PSGII; PS34
Tractability: Antibody: UniProt places it where antibodies can reach, with high confidence; UniProt predicts a signal peptide or a membrane-spanning region; its Gene Ontology location is reachable by antibodies, with medium confidence.
Gene: Protein-coding gene on chromosome 19 (43,211,791 to 43,269,530, reverse strand). Ensembl gene ENSG00000183668.
Subcellular location: Secreted
Pathways (Reactome):
Hemostasis: Cell surface interactions at the vascular wall
Gene Ontology:
Molecular function: protein binding; protein-containing complex binding
Biological process: Fc receptor mediated inhibitory signaling pathway; negative regulation of cytokine production involved in inflammatory response; positive regulation of SMAD protein signal transduction; regulation of regulatory T cell differentiation; tolerance induction dependent upon immune response; transforming growth factor beta receptor signaling pathway; female pregnancy
Cellular component: transforming growth factor beta ligand-receptor complex; extracellular region
Genetic constraint (gnomAD): Loss-of-function variants: 47 observed, 40.66 expected, observed/expected ratio (o/e) 1.16, 90% interval 0.91 to 1.47. The synonymous counts are far from expectation, so gnomAD's model fits this gene poorly and the ratio says little. Missense variants: 635 observed, 517.42 expected, observed/expected ratio (o/e) 1.23, 90% interval 1.15 to 1.31. Synonymous variants: 258 observed, 194.99 expected, observed/expected ratio (o/e) 1.32, 90% interval 1.19 to 1.47.
Homologues: Orthologues: chimpanzee PSG9 (94% identical). Paralogues in human: PSG6 (88% identical), PSG3 (85% identical), PSG8 (85% identical), PSG4 (84% identical), PSG7 (84% identical), PSG1 (83% identical), PSG5 (65% identical), PSG2 (62% identical), PSG11 (62% identical), CEACAM1 (41% identical), CEACAM5 (38% identical), CEACAM8 (36% identical), and 12 more.
Diseases named in the same sentence as PSG9 in open-access papers:
PSG9 is named in the same sentence as 25 diseases in open-access papers, as found by Europe PMC text mining. Sharing a sentence is not in itself a finding about the gene and the disease. The quoted sentences say what the papers report.
preeclampsia (7 papers, 2014 to 2026). Preeclampsia is a hypertensive disorder of pregnancy that is characterized by new-onset hypertension with proteinuria presenting after 20 weeks of gestation, and depending on mild or severe forms may initially present with severe headache, visual disturbances, and hyperreflexia. "Previous clinical cohort studies have implicated increased levels of circulating PSG7 and PSG9 with preeclampsia." (PMID 40991151, 2025). "We explored changes in pregnancy-specific glycoprotein 9 (PSG9) levels in the serum of patients with preeclampsia and the effects and underlying mechanisms of PSG9 effects on calcium (Ca2+) homeostasis and nitric oxide (NO) release in human umbilical vein endothelial cells (HUVECs)." (PMID 36980442, 2023). "PSG11 gene copy-number loss and increased PSG9 levels are associated with a higher risk for preeclampsia, a serious pregnancy complication characterized by high blood pressure and proteinuria, also indicate different roles of PSGs in the establishment and maintenance of successful pregnancies." (PMID 33602137, 2021). "However, an association between PSG9 and the occurrence or development of preeclampsia remains unclear." (PMID 36980442, 2023). "Therefore, we speculate that this decrease in PSG9 levels may be associated with the occurrence of preeclampsia." (PMID 36980442, 2023). "Given the association between DLX5/GATA3 dysregulation and elevated PSG9 levels, along with PSG9's expression in the first trimester, PSG9 shows potential as a predictive biomarker for preeclampsia." (PMID 41796334, 2026). "Therefore, PSG9 may regulate endothelial cell function through a Ca2+/eNOS/NO signaling pathway, leading to changes in vascular tension, and may be associated with the occurrence or development of preeclampsia." (PMID 36980442, 2023). "In the present study, we confirmed that the PSG9 expression levels in the peripheral blood of patients with preeclampsia were lower than those in healthy pregnant women, consistent with the results from our previous iTRAQ study." (PMID 36980442, 2023). "Compared with those in healthy pregnant women, PSG9 levels were significantly decreased in blood samples collected from pregnant women with preeclampsia." (PMID 36980442, 2023). "In our previously published study, serum PSG9 levels identified by LC-MS/MS were significantly decreased in the patients with preeclampsia compared with those in the healthy control pregnant women." (PMID 36980442, 2023). "Compared with those in healthy pregnant women, serum PSG9 levels were significantly decreased in patients with preeclampsia." (PMID 36980442, 2023). "Western blotting analyses were used to verify the PSG9 serum level changes in patients with preeclampsia." (PMID 36980442, 2023). "By using iTRAQ technology, we previously found that the expression levels of PSG9 in the serum of pregnant women with preeclampsia were significantly decreased compared with healthy pregnant women." (PMID 36980442, 2023). "Our data showed that serum PSG9 protein levels were significantly decreased in the patients with preeclampsia compared with those in the healthy controls." (PMID 36980442, 2023). "In summary, we found that serum PSG9 levels were significantly decreased in pregnant women with preeclampsia." (PMID 36980442, 2023). "This study clarified only the role of PSG9 in vascular endothelial cells to suggest its role in the pathogenesis of preeclampsia." (PMID 36980442, 2023). "The study of PSG9 is of particular interest as its levels have been found by mass spectrometry to differ at 15-weeks’ gestation between women diagnosed with early-onset preeclampsia and healthy controls." (PMID 27389696, 2016). "In addition to clarifying a molecular mechanism whereby PSG9 regulates the function of vascular endothelial cells, these findings suggest that PSG9 may warrant further study for the prevention or treatment of preeclampsia." (PMID 36980442, 2023).
preeclampsia (continued). "Aberrant and persistent production of pro-inflammatory cytokines and chemokines can lead to a variety of pregnancy disorders including pre-term birth, fetal growth restriction and preeclampsia and therefore we focused on determining whether PSG9 is able to reduce their expression." (PMID 27389696, 2016). "There is evidence that adverse pregnancy outcomes, such as fetal growth restriction, premature delivery, and preeclampsia, are related to reduced blood levels of PSG1 in pregnant women, but there are few reports examining PSG9." (PMID 36980442, 2023). "Although differences in levels of PSG7, PSG9 and PSG1 proteins (all encoded by polymorphic pseudogenes) have been proposed as biomarkers for preeclampsia, no information regarding the individual genetic variability of these genes was provided in these studies." (PMID 39488654, 2024).
colorectal cancer (5 papers, 2005 to 2025). A primary or metastatic malignant neoplasm that affects the colon or rectum. "In agreement with our observations, another study recently reported that PSG9 is distributed in the cell membrane, cytoplasm, and nucleus of human umbilical vein endothelial cells and colorectal cancer cells." (PMID 33377651, 2020). "PSG9 expression was also detected in 70% (42/60) of sporadic colorectal cancers, while only 8% (5/60) of the corresponding normal mucosa showed even low levels of PSG9 expression." (PMID 15982419, 2005). "Further analysis of sporadic and familial colorectal cancer confirmed that PSG9 is ectopically upregulated in vivo by cancer cells." (PMID 15982419, 2005). "To determine the degree of PSG9 deregulation in colorectal cancer we employed RNA in situ hybridization." (PMID 15982419, 2005). "The coding sequences of all PSG9 variants of two colon cancer cell lines (SW620 and LoVo) and two sporadic colorectal cancer cases were cloned and sequenced." (PMID 15982419, 2005). "In this context, very limited evidence has shown that PSG9 protein levels are significantly increased in hepatocellular carcinoma and colorectal cancer patients and could serve as an indicator of patient prognosis." (PMID 33377651, 2020). "PSG9 expression was also examined in a panel of colorectal cancer cell lines." (PMID 15982419, 2005). "Notably, PSG9 was expressed in the morphologically normal mucosa of FAP patients with APC germline mutations, while its expression was rarely detectable in normal mucosa of sporadic colorectal cancers using in situ hybridization." (PMID 15982419, 2005). "In colorectal cancer (CRC), PSG9 has been shown to promote angiogenesis through interaction with SMAD4, leading to enhanced nuclear retention of SMAD4 and activation of angiogenesis-related genes such as VEGFA and PDGF-AA." (PMID 40806565, 2025). "PSG9 is a member of the pregnancy-specific glycoprotein (PSG) family and has been shown to contribute to the progression of colorectal cancer (CRC) and cancer-related angiogenesis." (PMID 27528036, 2016). "In total, deregulation of PSG9 mRNA was detected in 78% (14/18) of FAP adenomas and 75% (45/60) of sporadic colorectal cancer cases tested." (PMID 15982419, 2005). "PSG9 RNA transcripts were detected at higher levels and at earlier stages in FAP cases than sporadic colorectal cancer." (PMID 15982419, 2005). "Since PSG9 is not found in the non-pregnant adult except in association with cancer, and it appears to be an early molecular event associated with colorectal cancer monitoring of its expression may be useful as a biomarker for the early detection of this disease." (PMID 15982419, 2005).
lung adenocarcinoma (3 papers, 2021 to 2024). A carcinoma that arises from the lung and is characterized by the presence of malignant glandular epithelial cells. "For example, TFAP2A enhances the metastatic ability of lung adenocarcinoma through the miR-16/TFAP2A/PSG9/TGF-β axis and promotes the progression of lung adenocarcinoma through epithelial–mesenchymal transition (EMT) by inducing the expression of KRT16." (PMID 39695171, 2024). "In addition, the mRNA level of PSG9 significantly increased with an increase in the transcription factor AP-2α (TFAP2A) in lung adenocarcinoma, which predicts poorer OS and PFS, probably because of the promotion of tumor metastasis." (PMID 36276966, 2022).
breast carcinoma (2 papers, 2020 to 2022). "As expected, high plasma PSG9 levels were associated with poor DFS of breast cancer patients (P = .00043)." (PMID 33377651, 2020). "First, PSG9 is upregulated in tumor tissues and plasma samples from breast cancer patients and its high expression is associated with poor prognosis." (PMID 33377651, 2020). "Here, we report that PSG9 expression levels were elevated in tumor tissues and plasma specimens from breast cancer patients, and were associated with poor prognosis." (PMID 33377651, 2020). "Gain‐ or loss‐of‐function studies demonstrated that PSG9 promoted breast cancer cell proliferation, migration, and invasionin vitro, and enhanced tumor growth and lung colonization in vivo." (PMID 33377651, 2020). "Collectively, both bioinformatic and experimental data suggest that PSG9 is upregulated in breast tumors and is associated with poor prognosis of breast cancer patients." (PMID 33377651, 2020). "To address the molecular mechanisms underlying the noted upregulation and oncogenic role of PSG9 in breast cancer cells, we analyzed the promoter sequence of the human PSG9 gene within 1‐kb region upstream from the transcriptional start site." (PMID 33377651, 2020). "Moreover, plasma PSG9 levels were also elevated in breast cancer patients and were associated with poor clinical outcome." (PMID 33377651, 2020). "In summary, findings presented here underscore the pivotal role of PSG9 in breast cancer progression and canonical TGF‐β/Smad pathway." (PMID 33377651, 2020). "As PSG9 enhances the stability of Smad2/3/4, there are two possibilities for the contribution of PSG9 to breast cancer cell proliferation and tumor growth." (PMID 33377651, 2020). "Functional and mechanistic investigations demonstrated that PSG9 promotes breast cancer progression by acting as both a direct transcriptional target and a positive regulator of the canonical TGF‐β/Smad signaling." (PMID 33377651, 2020). "Together, these data confirm that PSG9 enhances migratory, invasive, and metastatic potential of breast cancer cells both in vitro and in vivo." (PMID 33377651, 2020). "As PSG9 is a secreted glycoprotein, it is interesting to carry out a population‐based cohort study to examine the possibility of PSG9 as a potential plasma biomarker for the prediction and/or prognosis of breast cancer." (PMID 33377651, 2020). "Bioinformatics analysis of multiple publicly available datasets revealed aberrant PSG9 expression in breast tumors, but its functional and mechanistic role in breast cancer remains unexplored." (PMID 33377651, 2020). "Collectively, these findings establish PSG9 as a novel player in breast cancer progressionvia hijacking the canonical TGF‐β/Smad signaling, and identify PSG9 as a potential plasma biomarker for the early detection of breast cancer." (PMID 33377651, 2020). "Our findings establish PSG9 as a novel player in breast cancer progression via hijacking the canonical TGF‐β/Smad signaling and identify PSG9 as a potential plasma biomarker for the early detection of breast cancer." (PMID 33377651, 2020). "To determine the functional role of PSG9 in breast cancer progression, we first examined PSG9 expression levels by immunoblotting in normal HMEC and multiple breast cancer cell lines, including HCC1806, HCC1937, SUM159, Hs578T, MDA‐MB‐453 (MDA‐453), and BT549." (PMID 33377651, 2020). "To define the prognostic significance of PSG9 expression in breast cancer patients, we then performed IHC staining of PSG9 in 161 surgical specimens from patients diagnosed with invasive breast cancer with an anti‐PSG9 antibody." (PMID 33377651, 2020). "In this study, we uncovered several interesting findings concerning the emerging role of PSG9 in breast cancer progression." (PMID 33377651, 2020). "Together, these results suggest that PSG9 promotes breast cancer cell proliferation and colony formation in vitro and enhances xenograft tumor growth in vivo." (PMID 33377651, 2020).
breast carcinoma (continued). "Results showed that PSG9 was frequently upregulated in breast cancer cell lines compared to normal HMEC control." (PMID 33377651, 2020). "To further explore the potential prognostic value of the plasma levels of PSG9, we detected PSG9 levels in plasma specimens from 161 breast cancer patients by ELISA." (PMID 33377651, 2020). "One drawback of this story is that it remains unexplored how PSG9 promotes breast cancer cell proliferation and tumor growth." (PMID 33377651, 2020). "As a feature of breast cancer cells is their invasive and metastatic capacity, we next determined whether PSG9 could affect the migratory and invasive potential of breast cancer cells." (PMID 33377651, 2020). "Together, these bioinformatic data indicate that dysregulation of PSG9 may contribute to breast cancer progression." (PMID 33377651, 2020). "PSG9 levels in breast cancer patients were higher than those in normal subjects." (PMID 33377651, 2020). "Second, PSG9 may potentiate TGF‐β‐induced Smad‐mediated transcriptional response to regulate breast cancer cell proliferation." (PMID 33377651, 2020). "First, the stabilized Smad3 by PSG9 could regulate breast cancer cell proliferation and tumor growth." (PMID 33377651, 2020). "Similarly, the elevated expression of PSG9 in plasma specimens and tumorous tissue was strongly associated with poor clinical and prognostic parameters, such as metastatic lymph node tissues, distant metastasis, and shorter DFS in breast cancer patients." (PMID 36276966, 2022). "In this study, we demonstrated that PSG9 is involved in TGF‐β1‐induced EMT and breast cancer cell migration and invasion." (PMID 33377651, 2020). "Consequently, PSG9 contributed to TGF‐β1‐induced epithelial‐mesenchymal transition (EMT) and breast cancer cell migration and invasion." (PMID 33377651, 2020). "As PSG9 is a secreted glycoprotein, we next measured plasma levels of PSG9 in 20 healthy, nonpregnant females and 60 breast cancer patients by ELISA." (PMID 33377651, 2020). "Thus, whether PSG9 in turn induces secretion and activation of TGF‐β1 in breast cancer cells remains to be addressed in the future studies." (PMID 33377651, 2020). "Moreover, PSG9 enhanced the stability of Smad2, Smad3, and Smad4 proteins by blocking their proteasomal degradation, and regulated the expression of TGF‐β1 target genes involved in EMT and breast cancer progression, thus further amplifying the canonical TGF‐β/Smad signaling in breast cancer cells." (PMID 33377651, 2020).
fetal growth restriction (2 papers, 2023 to 2024). A fetus that does not grow beyond the 10th percentile of conventionally accepted weight for gestational age. "Our findings are consistent with previous work on PSGs and fetal growth restriction indicating that increased expression of PSG9 is associated with decreased total GWG." (PMID 38854080, 2024).
hepatocellular carcinoma (2 papers, 2020 to 2022). A malignant tumor that arises from hepatocytes. "In hepatocellular carcinoma, two studies consistently demonstrated that significantly increased PSG9 protein in the plasma exerted an important regulatory impact on tumor proliferation and progression and served as a self-contained biomarker for predicting prognosis." (PMID 36276966, 2022).
adenoma (1 paper, 2005). A neoplasm arising from the epithelium. "Transcripts of PSG9 were detected in 78% (14/18) of adenomas from FAP cases with APC germline mutations." (PMID 15982419, 2005). "High levels and early deregulation of PSG9 in adenomas, as well as normal mucosa in some FAP cases, indicates the potent role of APC germline mutations that are often found in these cases." (PMID 15982419, 2005). "Early expression of PSG9 even before adenoma formation at the top of the crypts in FAP cases, suggests that transformation process starts in cells at the top of the crypts which then gradually move downward." (PMID 15982419, 2005). "Pregnancy specific β1 glycoprotein 9 (PSG9) showed a consistent two fold up-regulation in adenomas compared to normal mucosa and as the most statistically significant candidate in these experiments (p < 0.006) was selected for further analysis." (PMID 15982419, 2005). "Our results provide strong evidence that PSG9 deregulation in cells occurs early during adenoma-carcinoma formation." (PMID 15982419, 2005). "Detection of PSG9 expression in adenomas, and at higher levels in FAP cases, indicates that germline APC mutations and defects in Wnt signalling modulate PSG9 expression." (PMID 15982419, 2005). "Nuclear β-catenin could be detected in all sporadic tumours, while staining was less intense in the normal-appearing epithelium and adenomas in FAP cases where PSG9 was highly upregulated." (PMID 15982419, 2005).